VTCN1 (V-set domain containing T cell activation inhibitor 1)
Description:
Negatively regulates T-cell-mediated immune response by inhibiting T-cell activation, proliferation, cytokine production and development of cytotoxicity. When expressed on the cell surface of tumor macrophages, plays an important role, together with regulatory T-cells (Treg), in the suppression of tumor-associated antigen-specific T-cell immunity. Involved in promoting epithelial cell transformation.
Synonyms: B7-H4; B7H4; FLJ22418; B7S1; B7x; B7h.5; PRO1291; VCTN1
Tractability: Antibody: UniProt places it where antibodies can reach, with medium confidence; UniProt predicts a signal peptide or a membrane-spanning region; its Gene Ontology location is reachable by antibodies, with medium confidence; the Human Protein Atlas places it where antibodies can reach.
Gene: Protein-coding gene on chromosome 1 (117,143,587 to 117,210,960, reverse strand). Ensembl gene ENSG00000134258.
Subcellular location: Cell membrane
Subcellular location (Human Protein Atlas): Plasma membrane; Cell Junctions; Focal adhesion sites
Gene Ontology:
Molecular function: protein binding; signaling receptor binding
Biological process: negative regulation of apoptotic process; negative regulation of T cell activation; negative regulation of T cell proliferation; regulation of cytokine production; T cell receptor signaling pathway; regulation of T cell proliferation
Cellular component: external side of plasma membrane; plasma membrane
Genetic constraint (gnomAD): Loss-of-function variants: 26 observed, 27.34 expected, observed/expected ratio (o/e) 0.95, 90% interval 0.7 to 1.32. The upper end of that interval is the gene's LOEUF score, 1.32, which puts it in group 5 of 6, group 1 being the genes least tolerant of losing a copy. Missense variants: 298 observed, 350.88 expected, observed/expected ratio (o/e) 0.85, 90% interval 0.77 to 0.94. Synonymous variants: 116 observed, 136.05 expected, observed/expected ratio (o/e) 0.85, 90% interval 0.73 to 1.
Homologues: Orthologues: macaque VTCN1 (99% identical), chimpanzee VTCN1 (96% identical), dog VTCN1 (94% identical), pig VTCN1 (91% identical), guinea pig VTCN1 (88% identical), mouse Vtcn1 (88% identical), rabbit VTCN1 (82% identical), rat Vtcn1 (81% identical), tropical clawed frog vtcn1 (38% identical), tropical clawed frog vtcn1 (31% identical), zebrafish vtcn1 (30% identical). Paralogues in human: BTNL3 (23% identical), BTN2A1 (23% identical), BTN1A1 (22% identical), BTN3A1 (22% identical), HHLA2 (22% identical), BTN3A3 (22% identical), BTN2A2 (21% identical), BTNL8 (21% identical), BTNL9 (21% identical), CD276 (21% identical), BTN3A2 (20% identical), BTNL2 (19% identical), and 3 more.
Diseases named in the same sentence as VTCN1 in open-access papers:
VTCN1 is named in the same sentence as 145 diseases in open-access papers, as found by Europe PMC text mining. Sharing a sentence is not in itself a finding about the gene and the disease. The quoted sentences say what the papers report.
breast cancer (54 papers, 2008 to 2025). A primary or metastatic malignant neoplasm involving the breast. "BLIS represents a subset of breast cancers linked with high recurrence rates and has been shown to highly express VTCN1 which encodes for B7-H4 that negatively regulates T cell activation." (PMID 36050786, 2022). "Some SNPs in six immunological genes, BTLA, ITGAL, CTLA4, ICOS, PDCD1, and VTCN1 were reported as breast cancer risk mutations in previous studies." (PMID 27911271, 2017). "In the checkpoint module, CD24 and VTCN1 were recognized as more active signaling pathways related to immune escape in breast cancer with high RiskScore." (PMID 40337509, 2025). "Several recent studies have shown that VTCN1 is often overexpressed in tumor tissues of ovarian, lung, and breast cancers." (PMID 35774278, 2022). "Recently, it was discovered that VTCN1 is related to the metastasis of melanoma, prostate cancer, renal cell carcinoma, breast cancer, and ovarian cancer." (PMID 34367975, 2021). "B7-H4 (encoded by VTCN1) is an immune checkpoint ligand in the CD28/B7 family of molecules characterized by sequence similarity to other B7 family proteins and is expressed in several human tumor types, including breast cancer." (PMID 38687247, 2024). "VTCN1 is also expected to be an antibody‐mediated therapeutic target for breast cancer." (PMID 28255028, 2017). "Recently, HIF1A has been shown to induce VTCN1 in multiple myeloma, cervical, and breast cancer cell lines, which may be a part of the mechanism by which VTCN1 is regulated in IMA." (PMID 28255028, 2017). "Our analysis identified elevated levels of immune-relevant proteins, including VTCN1, CD274, and CD73, specifically within the basal-like subtype of breast cancer (BLBC), compared to other subtypes." (PMID 40229283, 2025). "The plasma membrane protein B7-H4 (VTCN1) is expressed in ovarian, endometrial, and breast cancers, among other tumor types." (PMID 39456611, 2024). "Similar to VTCN1, CD276 is mainly expressed on tumor cells, such as lung cancer, renal cell carcinoma, breast cancer, endometrial cancer, and ovarian cancer cells." (PMID 34367975, 2021). "To evaluate the different responses to immunotherapy among the subtypes, we analyzed the mRNA expression of breast cancer immune checkpoint genes, namely PD-1, PD-L1, PD-L2, LAG3, VTCN1, IDO1, and TIM3." (PMID 34277633, 2021). "These include VTCN1 and CDKN2B, whose functional role in breast cancer downstream of this pathway requires further investigation." (PMID 18652687, 2008).
ovarian carcinoma (51 papers, 2008 to 2025). A malignant neoplasm originating from the surface ovarian epithelium. "In patients with ovarian carcinoma and glioma, macrophages expressing VTCN1 have been directly linked to inhibition of T cell immune response." (PMID 31101122, 2019). "VTCN1 (V-set domain containing T cell activation inhibitor 1), has been suggested as a possible target for treatment, as its overexpression has been linked to viability and metastasis in ovarian cancer." (PMID 35406529, 2022). "Importantly, B7H4-targeting antibodies show promising antitumour effects in ovarian cancer models, and clarifying VTCN1 function can be crucial for obtaining optimal treatment effects." (PMID 39061159, 2024). "In ovarian cancer, TAMs expressing B7-H4 (a member of the B7 superfamily; V-set domain containing T cell activation inhibitor 1, gene) suppress the activation of antigen-specific T-cells; and CCL22 secreted by TAMs recruits CCR4-expressing Tregs and promotes tumour growth." (PMID 32937961, 2020). "Among the potential ADC targets in ovarian cancer, the immune checkpoint molecules B7-H3 (also known as CD276) and B7-H4 (also referred to as VTCN1, B7x, or B7S1) have emerged as particularly promising due to their overexpression in ovarian tumors and their role in immune evasion." (PMID 41357243, 2025). "The mentioned cytokines did not increase VTCN1 expression in vitro, indicating that other factors may be necessary for B7H4 induction in ovarian cancer." (PMID 39061159, 2024).
glioma (42 papers, 2016 to 2025). A benign or malignant brain and spinal cord tumor that arises from glial cells (astrocytes, oligodendrocytes, ependymal cells). "The expression of immune checkpoints was significantly increased in the high-risk group except for VTCN1, indicating a close relationship with glioma immune escape." (PMID 35756689, 2022). "TOX was strongly correlated with CD276, IDO1, PDCD1LG2 (PD-L2), and VTCN1 in pan-glioma analysis and GBM alone in both TCGA and CGGA cohorts." (PMID 32762688, 2020). "TOX had high correlation with CD276, IDO1, PDCD1LG2, and VTCN1 in both pan-glioma analysis and GBM alone." (PMID 32762688, 2020). "It has been shown that the B7 family members, especially B7-H1 (PD-L1), B7-H3 (CD276), and B7-H4 (VTCN1), are involved in immune escape in several types of tumors including glioma." (PMID 32322592, 2020). "Furthermore, we found that 5 immune inhibitors (KDR, TIGIT, VTCN1, LAG3 and ADORA2A) and 2 immune stimulators (ICOS and TNFRSF25) were significantly associated with HIC2 in gliomas." (PMID 36650953, 2023). "Considering the successes in immune modulation for treating cancers, TET1 is a potential marker for predicting whether the gliomas would be responsive to biological agents that target Il-9 and VTCN1." (PMID 32483272, 2020). "Immune checkpoint blockade was an important strategy for glioma treatment; several regular checkpoint molecules were included in our study, and it indicated that except for PVRIG, CD200, and VTCN1, immune checkpoints were substantially higher in the high-risk group." (PMID 36281290, 2022).
lung carcinoma (28 papers, 2011 to 2026). "The results showed that in EGFR mutation-positive lung cancer, not only the density and function of CD8+ tumor-infiltrating lymphocytes are suppressed, the PD-L1 genes CD274 and CD86 are also downregulated, and HHLA2 and VTCN1 (B7-H4) were upregulated." (PMID 36910653, 2023). "Our findings indicate that the combination of CEACAM1, TNFSF4, GEM, CD47, VTCN1, and TANlncSig in squamous cell carcinoma can effectively stratify patients by prognosis, highlighting these immune checkpoint receptors as potential therapeutic targets against advanced lung cancer." (PMID 36386809, 2022). "VTCN1 also belonged to the B7 family, but its expression was not related to B cell and T cell infiltration in lung cancer." (PMID 32699529, 2020).
renal cell carcinoma (21 papers, 2011 to 2024). "High levels of VTCN1 have been observed in invasive breast cancer, and high tumor cell expression has been linked to disease progression and poor prognosis in renal cell cancer, suggesting that VTCN1 promotes tumor invasion." (PMID 37008954, 2023).
pancreatic cancer (17 papers, 2015 to 2022). "A previously unidentified VTCN1/NRG1 fusion was detected which is a known driver fusion event in pancreatic cancer that lacks KRAS driver mutations." (PMID 34504655, 2021). "Sequencing of a new metastatic lesion using GEM ExTra® revealed a VTCN1/NRG1 oncogenic fusion that is most likely the driver event of the pancreatic cancer." (PMID 34504655, 2021).
cervical carcinoma (14 papers, 2016 to 2025). A carcinoma arising from either the exocervical squamous epithelium or the endocervical glandular epithelium. "Experimental silencing of VTCN1 in cervical cancer models resulted in increased tumor suppressor retinoblastoma protein mRNA levels and decreased expression of the HPV E7 oncoprotein, implicating B7-H4 in the E7/Rb regulatory axis." (PMID 41211166, 2025). "In cervical carcinoma, VTCN1 exhibited a negative correlation with OGG1 and RAD51B methylation that was statistically significant after Bonferroni correction (p=0.009, p=0.015, respectively)." (PMID 27683114, 2016).
melanoma (14 papers, 2011 to 2025). A malignant, usually aggressive tumor composed of atypical, neoplastic melanocytes. "In the past few years, B7-H4 (B7S1/VTCN1/B7x), a member of B7/CD28 superfamily, has been studied in many kinds of malignant tumors, including breast, lung, gastric, pancreatic, colorectal, melanoma and prostate cancer." (PMID 28978159, 2017).
autoimmune disease (13 papers, 2009 to 2026). A disorder resulting from loss of function or tissue destruction of an organ or multiple organs, arising from humoral or cellular immune responses of the individual to their own tissue constituents. "Our study did not detect an association of previously identified autoimmune disease risk SNPs (rs2358817 within VTCN1 gene; rs1049550 within ANXA11 gene; rs6679356 within IL12RB2 gene andrs9865818 within LPP gene) with T1DM in Croatian T1DM trio families." (PMID 23152861, 2012). "Vtcn1, also known as B7–H4, is similar to Serpinb2, it is not directly related to pain; however, its importance in immune response has made it a therapeutic target for the treatment of tumors, inflammation, autoimmune diseases, and organ transplantation." (PMID 38813203, 2024).
hepatocellular carcinoma (13 papers, 2016 to 2025). A malignant tumor that arises from hepatocytes. "VTCN1 (a T cell activation suppressor 1), also known as B7-H4, can regulate T cell activation in non-small-cell lung cancer, hepatocellular carcinoma, and prostate cancer." (PMID 35774278, 2022).
breast tumor (12 papers, 2010 to 2024). "The adaptive immune checkpoints BTNL9 and VTCN1 and the innate immune checkpoints CD200 and SIRPA were downregulated in breast tumor tissues while the metabolic immune checkpoints ADORA2A and TDO2 were upregulated in breast tumor tissues." (PMID 33932112, 2021). "Furthermore, 72 CSRs showed higher expression in breast tumours versus non-breast healthy tissues, including VTCN1 (log2FC = 7.0), LRRC (5.8), and SLITRK6 (5.5)." (PMID 38306344, 2024).
bladder cancer (10 papers, 2014 to 2025). "Up-regulation of the VTCN1 expression in bladder cancer led to poor survival." (PMID 33092083, 2020). "B7x (B7-H4, B7S1, or VTCN1), a member of the B7/CD28 family, is frequently expressed in advanced bladder cancer, yet its role in bladder cancer progression and resistance to therapy remains poorly understood." (PMID 42004225, 2025).
endometrial cancer (9 papers, 2014 to 2025). Primary or metastatic malignant neoplasm involving the endometrium (mucous membrane that lines the endometrial cavity). "The interplay between methylation and immune cell distribution, analyzed via algorithms like CIBERSORT, reveals VTCN1-driven immunosuppression as a key mechanism in endometrial cancer development." (PMID 41029427, 2025). "Endometrial cancer highlights hypomethylation-driven immunosuppression via VTCN1, underscoring the need for tailored epigenetic interventions." (PMID 41029427, 2025). "The results showed that VTCN1 is indeed negatively correlated with CD8+ T cells in endometrial cancer, and there was lower T cell infiltration in tumor tissues in the high VTCN1 expression group." (PMID 35774278, 2022). "To further explore whether VTCN1 is involved in regulating the occurrence and development of endometrial cancer through immune factors, we analyzed the level of immune cell infiltration in normal and tumor tissues." (PMID 35774278, 2022). "We further explored the mechanism by which VTCN1 is involved in endometrial cancer." (PMID 35774278, 2022). "Our study demonstrated that VTCN1 may be involved in the occurrence and development of endometrial cancer by inhibiting CD8+ T cell infiltration." (PMID 35774278, 2022). "In addition, immune regulation driven by the high expression of VTCN1 in tumors may promote the development of endometrial cancer by inhibiting CD8+ T cell infiltration." (PMID 35774278, 2022). "In endometrial cancer, DNA methylation regulates immune infiltration and immunotherapy potential through genes like VTCN1 (B7-H4)." (PMID 41029427, 2025).
clear cell renal cell carcinoma (5 papers, 2014 to 2024). "Some studies have also shown that VTCN1 has lower expression levels in clear cell renal cell carcinoma." (PMID 39116105, 2024).
colon cancer (5 papers, 2011 to 2024). "Most ICGs showed low mutation levels in colon cancer cases, except CD2, VTCN1, and LAYN." (PMID 34912802, 2021).
sarcoma (5 papers, 2014 to 2025). A usually aggressive malignant neoplasm of the soft tissue or bone. "High levels of tumour cell expression of LAG3, TIM3, and VTCN1 have been reported in multiple cancer types, including sarcoma, often in association with a worse clinical outcome, indicating an active role in promoting an immunosuppressive, tumour-promoting microenvironment." (PMID 35327375, 2022).
head and neck squamous cell carcinoma (4 papers, 2016 to 2025). A squamous cell carcinoma that arises from any of the following anatomic sites: lip and oral cavity, nasal cavity, paranasal sinuses, pharynx, larynx, and salivary glands. "For example, PD-L1 expression is increased in CD44+ breast cancer stem cells, CD133+ colorectal cancer stem cells, and CD44+ head and neck squamous cell carcinoma (HNSCC) stem cells; VTCN1 expression is also elevated in CD133+ glioblastoma stem cells." (PMID 39184916, 2024).
osteosarcoma (4 papers, 2015 to 2024). A usually aggressive malignant bone-forming mesenchymal neoplasm, predominantly affecting adolescents and young adults. "The role of VTCN1 in the osteosarcoma has been initially investigated by Qiang Dong and Xinlong Ma." (PMID 38225273, 2024). "Combining our result and previous studies, we hypothesized that, for osteosarcoma patients without response to anti-PD1/PDL1 therapy, targeting VTCN1 or HHLA2 was a potentially promising treatment method." (PMID 38225273, 2024).
leukemia (2 papers, 2017 to 2025). A malignant (clonal) hematologic disorder, involving hematopoietic stem cells and characterized by the presence of primitive or atypical myeloid or lymphoid cells in the bone marrow and the blood. "Thus, the effect of VTCN1 in the regulation of solid tumors and leukemia seems different: VCTN1 propagates CSCs in solid tumors but reduces LSCs in AML." (PMID 40175626, 2025).
squamous cell carcinoma (2 papers, 2018 to 2022). A carcinoma arising from squamous epithelial cells. "VTCN1 was detected in 3 of 13 patients with squamous cell carcinoma (22%), but not in any other patients." (PMID 30513627, 2018).
adenoid cystic carcinoma (1 paper, 2025). A malignant tumor arising from the epithelial cells. "Subtype specific expression of immune checkpoints is identified with prominent expression of VTCN1 in luminal-like cells within adenoid cystic carcinoma." (PMID 40506428, 2025).
colon adenocarcinoma (1 paper, 2022). "Analysis of the TCGA colon adenocarcinoma (COAD) dataset showed that the PRKCD mRNA level was also positively correlated with the VTCN1 (encoding B7-H4) mRNA level." (PMID 35410218, 2022).
pancreatic ductal adenocarcinoma (1 paper, 2021). An infiltrating adenocarcinoma that arises from the epithelial cells of the pancreas. "In PDAC, pancreatic ductal adenocarcinoma, over-expression of VTCN1 has been implicated in lymph node metastasis and unfavorable prognosis." (PMID 34504655, 2021).
skin melanoma (1 paper, 2022). "Furthermore, CD274 (PD-L1) expression correlated significantly with the rest immune checkpoints (apart from VTCN1) in skin melanoma compared to normal skin (not exposed to the sun), especially with PD-L2, ILT2, HAVCR2 and TIGIT." (PMID 36389735, 2022).